IL10 (interleukin 10)
Diseases named in the same sentence as IL10 in open-access papers (continued):
Sharing a sentence is not in itself a finding about the gene and the disease.
inflammatory bowel disease (continued). "On one hand, they exhibit IL-10-mediated regulatory functions that are protective for the gut, while on the other, they demonstrate direct cytotoxic activity that may contribute to the progression of inflammatory bowel disease." (PMID 41373807, 2025). "In a study of inflammatory bowel disease (IBD), exosomes derived from MSCs attenuated colonic mucosal inflammation by polarizing macrophages to an M2b-like phenotype with increased IL-10 production and secretion." (PMID 38779660, 2024). "With its pleiotropy in the immune system, IL-10 and its family of cytokines have been widely explored as therapeutic approaches in a wide variety of human diseases involving autoimmunity or excessive inflammation, such as rheumatoid arthritis, psoriasis, and inflammatory bowel disease." (PMID 39882328, 2024). "Patients with Inflammatory Bowel Disease are known to have selective loss of IL10 secretion from Tr1 cells, while IL10 production from FOXP3+ Tregs appears unaffected, further emphasizing a specific importance of Tr1s to IBD." (PMID 37654482, 2023). "Consistent with a protective role of IL-10 in inflammatory bowel diseases (IBD), effector CD4+ T cells from Crohn’s disease patients were defective in Notch/STAT3-induced IL-10 production and skewed towards an inflammatory Th1/17 cell phenotype." (PMID 35169232, 2022). "Many studies highlight the importance of the anti‐inflammatory IL‐10 axis in the physiopathology of inflammatory bowel disease (IBD)." (PMID 36169258, 2022). "Intervention with AG490 (a highly selective JAK2 inhibitor) in a rat model of inflammatory bowel disease (IBD) significantly decreased the levels of IL-6 and IL-17A and increased the levels of IL-10, suggesting a protective effect on IBD." (PMID 35590365, 2022). "Recombinant human IL-10 proved to be effective in the control of inflammatory bowel disease (IBD) and psoriasis." (PMID 34822503, 2021). "In humans, defective IL-10/IL-10R signalling has been shown to correlate with inflammatory bowel disease (IBD)." (PMID 34220850, 2021). "Subsequently, CD4+IL-10+ T cells were shown to exert immunosuppressive effects in various disease models, such as inflammatory bowel disease (IBD) and experimental autoimmune encephalomyelitis (EAE)." (PMID 34187557, 2021). "EVs isolated from MSCs used in the model of inflammatory bowel disease induced by tri-nitrobenzene sulfonic acid injection in rats, EVs derived from rat BM-MSCs attenuated colonic inflammation via a markedly decrease in IL-1β and an increase in IL-10 expression." (PMID 33613514, 2020). "Patients with loss-of-function mutations in IL10 or IL10 receptor (IL10R) genes develop severe, medical-refractory, infantile-onset inflammatory bowel disease (IBD)." (PMID 32117262, 2020). "For example, polysaccharide A, produced by B. fragilis, prevents inflammatory bowel disease (IBD) via an IL-10-producing CD4+ T cell-dependent mechanism." (PMID 31921196, 2019). "Previous studies with CD4-Cre-Il10fl/fl mice showed the spontaneous onset of inflammatory bowel disease (IBD) as mice aged, suggesting the crucial role of T cell-derived IL-10 in protecting mice from excessive inflammation." (PMID 31803193, 2019). "In this study, we used Il10−/−, a mouse model of human inflammatory bowel disease (IBD), and compared its transcriptomic responses to radiation with those of normal wild-type (WT) mice." (PMID 31046668, 2019). "Moreover, microbial translocation also occurs during inflammatory bowel disease (IBD), where intestinal inflammation and damaged barrier function results from a combination of factors, including dysbiosis and mutations in genes encoding proteins involved in the immune response, such as IL-10." (PMID 30640950, 2019). "IL-10 is a potent anti-inflammatory cytokine, and the results of IL-10 signaling are present in inflammatory bowel disease (IBD) patients and animal models." (PMID 29784012, 2018).
inflammatory bowel disease (continued). "Recombinant IL-10 has, therefore, been targeted to treat inflammatory diseases such as psoriasis and inflammatory bowel diseases (IBD), however with very limited clinical progress." (PMID 28671603, 2017). "The critical role of IL-10 in immune-mediated disorders is also demonstrated in human inflammatory bowel disease (IBD), a chronic, relapsing, idiopathic inflammation of the intestinal tract." (PMID 27611574, 2016). "IL-10 knockout mouse is another well-established mouse model of inflammatory bowel disease (IBD) wherein inflamed colon is characterized by inflammatory cell infiltration, crypt abscess formation, and epithelial hyperplasia." (PMID 27754373, 2016). "Interleukin-10 (IL-10) plays a central role in regulation of intestinal mucosal homeostasis and prevention of inflammatory bowel disease (IBD)." (PMID 27188220, 2016). "These IL-10−/− mice also develop spontaneously a Th1-mediated chronic enterocolitis, and have been widely used as an animal model of inflammatory bowel disease (IBD)." (PMID 24491821, 2014). "As an example, in a mouse animal model of inflammatory bowel disease (IBD), the beneficial effect of injected human adipose derived MSCs (hASCs) on the clinical and histological scores of mice was associated with an increased number of CD4+CD25+Foxp3+ and CD4+IL10+ cells in the lymph nodes." (PMID 23734780, 2013). "In fact, patients with IL-10 or IL-10 receptor defects develop an early-onset, severe, and monogenic inflammatory bowel disease (IBD) that is exceptionally hard-to-treat." (PMID 23382730, 2013). "IL-10 is the central anti-inflammatory cytokine well researched in the pathogenesis of Inflammatory Bowel Disease (IBD)." (PMID 22973511, 2012). "The active form of vitamin D (1,25(OH)2D3) has been shown to inhibit development of inflammatory bowel disease (IBD) in IL-10 KO mice." (PMID 17397543, 2007). "Importantly, IL-10 gene therapy increased body weight gain, reduced colon injury, and prevented the development of inflammatory bowel disease (IBD)." (PMID 41897417, 2026). "In a similar gene-transfer approach, high IL-10 production is induced by lentiviral transduction into CD4+ T cells (CD4LV-IL10) to produce allogenic type 1 regulatory T cells (Tr1 cells) for “off-the shelf” GvHD and inflammatory bowel disease (IBD) treatment in clinical trials led by Tr1X Bio." (PMID 41246323, 2025). "Supplementation with β-1,3–1,6-D-glucan to dogs with IBD reduces Canine Inflammatory Bowel Disease Activity Index (CIBDAI) values, increases levels of the anti-inflammatory cytokine interleukin (IL)-10, and improves histopathological parameters." (PMID 40359204, 2025). "Likewise, another study demonstrated that indole-3-propionic acid (IPA)-mediated AhR activation led to reduced IFN-γ production by DCs and promoted IL-10 producing T-cell differentiation in inflammatory bowel disease (IBD) in mice." (PMID 39211042, 2024). "IL-10 signalling has an important role in modulating mucosal inflammation in the intestine, and deletion of the cytokine or its receptor (IL-10R) results in severe inflammatory bowel disease (IBD) in both mouse and humans." (PMID 38383790, 2024). "Our findings suggest that resveratrol may exhibit anti-inflammatory effects in Inflammatory Bowel Disease (IBD) by increasing IL-10 levels and decreasing TNF-α, IL-6, IL-1β, and IL-8 levels." (PMID 38948464, 2024). "Similarly, the system demonstrated an effective anti-inflammatory effect in an inflammatory bowel disease (IBD) mouse model upon the delivery of interleukin 10 mRNA." (PMID 38965553, 2024). "Hookworm-derived recombinant proteins AIP-1 and AIP-2 have been shown to reduce inflammation in mouse models of inflammatory bowel disease and inflammatory airway disease by inducing CD4+Foxp3+ cells and IL-10 production." (PMID 38239430, 2023). "Butyrate modulates the release of IL10 and IL17, two central cytokines of the pathogenesis of inflammatory bowel disease (IBD)." (PMID 36977462, 2023).
inflammatory bowel disease (continued). "Interestingly, a wide variety of cytokines such as IL-13, IL-10, and TGFβ1 have been demonstrated to participate in the innate and adaptive immune response to inflammatory bowel disease (IBD)." (PMID 36776842, 2023). "However, this hypothesis is complicated by the finding that VEGFR3 blockade induces the development of dilated and tortuous lymphatics in the IL-10 knockout model of spontaneous inflammatory bowel disease (IBD), which was shown to worsen intestinal inflammation." (PMID 38201272, 2023). "We found that B. infantis mediated Foxp3 expression through PD-1/PD-L1 pathway, which promoted Tregs differentiation and improved IL-10 and TGF- β 1 expression, so as to reduce the immune and inflammatory response of mice with inflammatory bowel disease." (PMID 35860248, 2022). "Previous studies have shown that supplier-dependent differences in the GM significantly influence disease phenotypes in several disease models, such as the IL10−/− mouse model of inflammatory bowel disease (IBD) and the Apc+/min mouse model of colorectal cancer." (PMID 36380056, 2022). "Anti-inflammatory agent Interleukin-10 (IL10) is used in the treatment of clinical diseases such as rheumatoid arthritis, inflammatory bowel disease, psoriasis, chronic hepatitis C and atherosclerosis." (PMID 35455438, 2022). "Similarly, in humans, defective IL-10/IL-10R signaling has been shown to correlate with inflammatory bowel disease (IBD)." (PMID 36290283, 2022). "This toxicity is evident in two biologically different mouse models of inflammatory bowel disease, the AOM/DSS and the IL10−/− model." (PMID 33664327, 2021). "Mice lacking IL-10 in Tregs are highly susceptible to colitis using Inflammatory bowel disease (IBD) models and exhibit immune reactivity in the airways." (PMID 34675933, 2021). "Further, CD19hiCD1dhiCD5+ B cells produce IL10 and inhibit DSS-induced inflammatory bowel disease and experimental Sjögren’s syndrome by suppressing Tfh cell responses." (PMID 34594327, 2021). "IL-10 serves as an anti-inflammatory cytokine, which is increased after RSV administration in inflammatory bowel disease." (PMID 34497510, 2021). "Also, for inflammatory bowel disease (IBD), a persistent inflammatory response to gut bacteria, a significant increase in TCR in circulating lymphocytes of IL10/IL10R-deficient patients was observed." (PMID 33633732, 2020). "Cannabigerol (CBG) has exhibited protective properties in a murine model of inflammatory bowel disease (IBD) by regulating cytokine (IL-1β, IL-10, and interferon-γ) levels and inhibiting inducible nitric oxide synthase (iNOS) expression." (PMID 33584697, 2020). "While the overall diversity of the microbiota of both wild type and IL-10-/- were similar in young mice, the latter failed to increase in complexity as the mice matured and experienced changes in abundance of specific bacterial taxa that are associated with inflammatory bowel disease in humans." (PMID 33664728, 2020). "One important characteristic of IL-6 is the persistent activation in the whole process of inflammatory bowel disease and CRC, while the upregulations of other cytokines like TGF-β1, IL-10, and IL-23 only show up primarily during CRC development." (PMID 32855767, 2020). "Thus, pattern-recognition receptors (PRRs) activation induced IL-10 production plays a central role in regulation of intestinal mucosal homeostasis and prevention of inflammatory bowel disease (IBD)." (PMID 27188220, 2016). "One of the most relevant tolerogenic mechanisms induced by tolDC therapies in addition to Treg are Breg (most B10 or IL-10 producers) since they have demonstrated immunoregulatory functions in EAE, inflammatory bowel disease and collagen-induced arthritis." (PMID 27207486, 2016). "IL-10 is implicated in enhancing the ability of MSCs in anti-inflammatory application and hematopoietic stem cell transplantation (HSCT) in treatment of the inflammatory bowel disease (IBD)." (PMID 26528857, 2015).
inflammatory bowel disease (continued). "Together the data support the late effects of vitamin D on diseases like inflammatory bowel disease and multiple sclerosis where reducing IL-17 and IFN-γ, while inducing IL-4 and IL-10, would be beneficial." (PMID 25912039, 2015). "Here we report two murine models of inflammatory bowel disease: RAG-2−/− mice adoptively transferred with CD4+CD45RBhigh T cells; and IL-10−/− mice, accompanied by the infiltration of mononuclear cells in the liver." (PMID 24392145, 2014). "Indeed, Fc receptor–mediated effects contribute to the therapeutic response to infliximab and adalimumab in mouse models of inflammatory bowel disease (IBD), and patients with IBD only respond to full IgG1 anti-TNF therapies via macrophage IL-10 signaling." (PMID 40337865, 2025). "Essential roles include the immune genes (e.g., TLRs, NOD2, IL-10) in regulating microbial populations and maintaining barrier integrity, hence establishing a clear connection between dysbiosis and inflammatory disorders such as inflammatory bowel diseases (IBD)." (PMID 41246320, 2025). "Studies conducted on recombinant human IL-10 (rhIL-10) for inflammatory bowel disease (IBD) have shown weak and inconsistent efficacy, partly attributable to its short half-life and the presence of pro-inflammatory properties that may counterbalance its beneficial effects." (PMID 41009491, 2025). "This shows us that they targeted the specific expression of IL-10 in colonic mice models, with induced inflammatory bowel disease, without the systemic involvement of other organs." (PMID 40149692, 2025). "While IL-10 is known to be anti-inflammatory, IL-22 fulfills a proinflammatory role in many different tissues and is involved in numerous diseases, including inflammatory bowel disease (IBD), psoriasis, and cancer, making it an interesting target or potential therapeutic." (PMID 39447666, 2024). "Seven genes IL10, IL4, IL6, IFNG, IL1B, TNF and IL17A, were engaged in Inflammatory bowel disease." (PMID 36989283, 2023). "On the other hand, it is worth mentioning that the persistent S. Typhimurium infection model used in this work was established in our laboratory to evaluate whether prior S. Typhimurium infection plays a role in the development of inflammatory bowel disease (IBD) in an IL-10−/− mouse model." (PMID 35739937, 2022). "IL-10 production from both B and T cells has important immunosuppressive functions, but while CD4 specific IL-10 KO mice show indications of severe inflammatory bowel disease with a high penetrance, there is no such indication in B specific IL-10 KO mice." (PMID 35979356, 2022). "The expression of LPD in regulatory T cells (Treg) of IL-10–null mice (a mouse model of inflammatory bowel disease [IBD]) is higher than that in conventional T cells, and is involved in the physiological integrin activation of Treg cells, suggesting that LPD may have a key role in immune regulation." (PMID 36210930, 2022). "Similarly, TGF-β1-loaded Dex impaired Ag-specific Th1 and IL-17 responses and promoted IL-10 production and the generation of Tregs in murine models of experimental allergic encephalomyelitis (EAE) and inflammatory bowel disease (IBD), respectively." (PMID 31615107, 2019). "Moreover, adoptive transfer of CD69+ Tregs but not CD69−Tregs or CD69+ Tregs deficient in IL-10 dramatically prevented the development of inflammatory bowel disease (IBD) in mice." (PMID 30185773, 2018). "IL-10 is one of the cytokines conferring the anti-inflammatory effect, involved in the pathogenesis of various autoimmune diseases, including systemic lupus erythematosus (SLE) and inflammatory bowel diseases (IBD)." (PMID 29895319, 2018).
inflammatory bowel disease (continued). "In particular, an increased expression of Wnts and Frizzled receptors was reported in inflammatory bowel disease (IBD) and ulcerative colitis to exert both anti- and pro-inflammatory functions regulating the intestinal activated nuclear factor κB (NF-кB), TNFa release, and IL10 expression." (PMID 25644719, 2015). "Moreover, H. bilis has been used experimentally to induce inflammatory bowel disease (IBD) in mdr−/− and IL-10−/− knock-out mice, typhlocolitis in the C3H/HeN mice strain and cholesterol gallstone formation in C57L mice." (PMID 22348013, 2012). "Besides the induction of IL-10-producing CD8+ Treg, ZPS also induces immunosuppressive CD4+ Treg, which produce IL-10 and prevent pathological conditions such as inflammatory bowel disease (IBD) and experimental autoimmune encephalomyelitis (EAE)." (PMID 21234388, 2010). "Resident microbiota activates IL10-producing regulatory B cells through TLR2, MyD88, and PI3K pathways, which help maintain colonic homeostasis and reduce T cell activation, which is critical in the context of inflammatory bowel disease, including Crohn’s disease and ulcerative colitis." (PMID 39337678, 2024). "However, another previous study on inflammatory bowel disease (IBD) model demonstrated that galectin of Toxascaris leonine deliver a beneficial effect on dextran sodium sulfate (DSS) by exhibiting significantly increase of the levels of TGF-β and IL-10." (PMID 30068382, 2018). "Anti-cytokine AAbs are generally polyclonal IgG in nature, however, low titer, non-neutralizing IgA AAbs to interleukin-10 (IL-10) have been detected in the serum of patients with inflammatory bowel disease (IBD)." (PMID 31354706, 2019). "Furthermore, treatment of inflammatory bowel disease (IBD)-induced mice with compound 1 decreased myeloperoxidase activity in colonic extracts and modulated the colon length and serum levels of cytokines such as TNF–α, IFN–γ, IL–6, IL–1β, and IL–10." (PMID 37893090, 2023). "While Tregs are immunosuppressive in inflammatory bowel disease (IBD) and gastritis, they are converted by chronic inflammation to IL-17-producing Tregs, which do not produce IL-10 and are found in colon adenomas." (PMID 33668122, 2021).